NF1 (neurofibromin 1)
Diseases named in the same sentence as NF1 in open-access papers (continued):
Sharing a sentence is not in itself a finding about the gene and the disease.
glioma (continued). "NF1-associated CNS gliomas, therefore, typically arise from consequences of RAS/MAPK pathway alterations and show the absence of alterations of other genes that are associated with glial tumor development outside of NF1, such as BRAF, TERT, EGFR, IDH, and histone H3 mutations." (PMID 41168866, 2025). "Additionally, it is unclear whether biopsy offers significant clinical benefits, particularly when imaging findings are consistent with low-grade glioma, especially in patients with NF1." (PMID 41440192, 2025). "The NF1 loss-of-function (LOF) mutations occur in many cancer types, including pediatric cancers, with 10% to 15% of pediatric patients developing a low-grade glioma within the optic pathway and an additional 3% to 5% patients developing low-grade glioma outside of the optic pathway." (PMID 40111124, 2025). "Furthermore, differential expression of miRNAs can be observed in RASopathies and has been crucial for understanding the molecular signature of malignant peripheral nerve sheath tumors (MPNSTs) compared to pNFs, as well as high-grade gliomas versus low-grade gliomas in NF1." (PMID 39201250, 2024). "Notably, NF1-associated high-grade gliomas do not exhibit the IDH and histone H3 mutations frequently found in sporadic malignant gliomas." (PMID 39273062, 2024). "Among the JH MTB cohort of patients with IDH1 wild-type high-grade gliomas who received targeted therapies, trametinib monotherapy or in combination with dabrafenib conferred radiographic partial response in 75% of patients harboring BRAF or NF1 actionable mutations." (PMID 38143440, 2023). "The role of NF1 is an equally well-recognized mutation in glioma, albeit not as common." (PMID 37760597, 2023). "Furthermore, the pathogenetic interaction between NF1-null neoplastic astrocytes and NF1-heterozygous stromal cells (microglia and endothelial cells) is crucial because the production and modulation of growth factors are essential for glioma formation and growth." (PMID 37830595, 2023). "Conversely, BRAF alterations are rarely found in adult gliomas, although activation of the MAPK is seen in 70% of GBM through amplifications or fusions in EGFR/PDGFRA/MET/FGRF1/2/3 genes or mutations in MAPK pathway members particularly NF1, reported in 15% of GBM." (PMID 37124503, 2023). "By analyzing the regulatory mechanisms underlying the risk subclonal mutations, we found that the subclonal mutations of AHNAK and AHNAK2 in GBM and those of NF1 and PTEN in LGG could influence some important molecules and functions associated with glioma progression." (PMID 35496054, 2022). "However, whether NF1 plays a broader functional role in the regulation of the MES gene signature (MGS) in IDH-wt gliomas still remains to be established." (PMID 34399888, 2021). "Histology: In children, most tumors associated with NF1, whether arising from the optic pathway or the non-optic pathway, are low-grade gliomas, typically PAs, with low mitotic rates and proliferative indices." (PMID 33779771, 2021). "Notably, hallmark mutations in the IDH genes or H3.3 histone genes which are found in sporadic pediatric gliomas have not been identified in NF1-associated HGGs." (PMID 34885143, 2021). "DNA methylation assigned NF1-glioma to LGm6, a poorly defined IDH wild-type subgroup enriched with ATRX mutations, which may represent a point of therapeutic intervention, as previous studies have shown that loss of ATRX increases sensitivity to DNA-damaging agents." (PMID 31906320, 2020). "Thus, ALT was a feature of predominantly high-grade or non-PA NF1-associated gliomas, while abnormally long telomeres (in the absence of ALT) are present in a subset of low-grade astrocytomas." (PMID 31462295, 2019). "In addition, ETV5 function is required to sustain Nf1-deficient high-grade glioma growth, but had not been previously implicated in low-grade gliomas." (PMID 29787563, 2018).
glioma (continued). "In the light of the finding that human and mouse low-grade gliomas are composed of Olig2+ cells and that Olig2+ oligodendrocyte precursor cells (OPCs) give rise to murine high-grade gliomas, we sought to determine whether Olig2+ OPCs could be tumor-initiating cells for Nf1 optic glioma." (PMID 28525381, 2017). "Within the RAS pathway, the pan-RAS inhibitor RMC-7977 demonstrated significant preclinical efficacy in NF1-related tumor models, including MPNST and glioma." (PMID 41374990, 2025). "We obtained isogenic glioma stem cell models derived from mouse neural stem cells engineered to express constitutively active EGFRvIII and CRIPSR-mediated deletion of Nf1 and Pten (NPE cells)." (PMID 40430842, 2025). "Nevertheless, to the best of our knowledge, this is the first study to investigate the relationship between MET- or FDG-PET and alterations in driver genes, including EGFR, PTEN, NF1, and CDKN2A/B in gliomas." (PMID 40786409, 2025). "The RAS/MAPK signaling pathway also plays an important role in gliomagenesis, and the NF1 gene, which is a negative regulator of the RAS oncogene, is most commonly affected in adult-type gliomas." (PMID 39684714, 2024). "Leveraging several Nf1 GEM strains and two complementary optic nerve injury models, we now demonstrate that optic nerve damage is sufficient to induce the formation of gliomas." (PMID 38308315, 2024). "In low grade glioma with activation of the MEK/ERK pathway, aberrations in BRAF or NF1 MEK inhibition with trametinib or selumetinib revealed promising activity in pediatric patients." (PMID 36566461, 2023). "(2012) subsequently demonstrated that pediatric optic glioma in NF1+/-GFAPCKO mice arose from third ventricle as NSCs from this region were the cells that hyperproliferated in response to mutations characteristic of pediatric glioma, and not NSCs from the lateral ventricle subventricular zone." (PMID 38318325, 2023). "The results revealed that older age (≥ 52 years old), high-grade glioma, and high expression of AGTR1, NF1, and AxL were independent prognostic factors." (PMID 37291545, 2023). "None harbored alterations within genes of the MAP kinase signaling pathway (e.g., BRAF, KRAS, NF1, and PTPN11) that are also common in pediatric gliomas." (PMID 36437415, 2023). "Alterations in CDK4/6, CIC, FGFR2/3/4, FUBP1, KIT, MET, NF1, PEG3, RB1, and NTRK2 were additional factors correlated with the survival of different subtypes of gliomas." (PMID 36998447, 2023). "In glioma, another PKC family protein, PKCα, has been shown to phosphorylate NF1 in the cysteine/serine-rich domain, thereby promoting the ubiquitination and degradation of NF1." (PMID 37355626, 2023). "Optic Pathways Gliomas (OPG) account for 3–7% of all pediatric gliomas, with a higher incidence in patients affected by Neurofibromatosis type I (NF-1)." (PMID 35455578, 2022).
glioma (continued). "Most mouse models of glioma are generated by altering key signaling pathways disrupted in human gliomas, including Ras, EGFR, Akt, Rb, Pten, Nf1 and platelet-derived growth factor (PDGF)." (PMID 33869004, 2021). "The highest average scores for NF experts deciding the ‘need for new treatment’ were for malignant peripheral nerve sheath tumour (MPNST) and high grade glioma (HGG) for NF1; meningioma for NF2 and pain for SWN." (PMID 33903738, 2021). "We identified four manifestation groups for NF1 that are recommended for future platform trials: MPNST, benign peripheral nerve sheath tumours, cutaneous manifestations and high grade gliomas." (PMID 33903738, 2021). "The TRAM-01 trial is a phase II multicentric open-label basket trial including four groups (NF1 LGG, NF1 PNF, BRAF-fusion LGG, other MAPK-acitvated glioma)." (PMID 33026636, 2020). "In the NF1-glioma dataset, ALT was present in the majority of high-grade gliomas: 14 (of 23; 60%) in contrast to only 9 (of 47; 19%) low-grade gliomas (p = 0.0009)." (PMID 31462295, 2019). "Mechanistically miR-9 inhibits the proliferation and promotes the migration of glioma cells by directly targeting cyclic AMP response element-binding protein (CREB) and neurofibromin 1 (NF1), respectively." (PMID 30813461, 2019). "In the current study, we show that the NF1-LRD plays a critical role in suppressing glioma cell invasion both in vitro and in an orthotopic glioma mouse model." (PMID 30967630, 2019). "Since CHI3L1 is implicated as a driver of some aspects of mesenchymal behavior in GBM, our study raises the possibility of a mechanistic link between NF1 and mesenchymal phenotype, mediated in part by CHI3L1 that is produced by the neoplastic glioma cells." (PMID 29643433, 2018). "Recent data from the TCGA network revealed that Ras activation occur in 90% glioma patients through Receptor tyrosine kinases (RTKs), PTEN or NF-1 alterations." (PMID 28199986, 2017). "The prevalence of Olig2+ cells in human gliomas, coupled with recent findings that Olig2+ oligodendrocyte precursor cells (OPCs) are the cells of origin for murine malignant glioma, raises the possibility that OPCs might be another tumor-initiating cell population for Nf1 murine optic glioma." (PMID 28525381, 2017). "Current work is underway to use these lines as cellular substrates for glioma modeling, as part of the CTF NF1 Synodos Initiative." (PMID 28066715, 2016). "A tendency towards mutual exclusivity between the loss or mutation of NF1 and amplification or mutation of EGFR was observed using Fisher's exact tests, indicating that both types of alteration may be sufficient to activate the RAS-RAF-MEK-MAPK cascade in RMPAhigh gliomas." (PMID 27385209, 2016). "The genomic alterations in EGFR, PDGFRA, NF1, PTEN and PIK3CA were nearly exclusively found in the RMPAhigh gliomas." (PMID 27385209, 2016). "Nf1+/− microglia express high levels of meningioma-expressed antigen-5 (MGEA5) and CXCL12, and these were shown to act as glioma-promoting molecules." (PMID 25008045, 2014). "MiR-9 inhibited the proliferation and promoted the migration of glioma cells by directly targeting cyclic AMP response element-binding protein (CREB) and neurofibromin 1 (NF1), respectively." (PMID 23185366, 2012). "Using these strategies, brain tumor models have been developed by altering signaling pathways that are disrupted in human gliomas including Rb, Ras, AKT, Pten, NF1 amongst others." (PMID 21896959, 2011).
glioma (continued). "These genes had varying degrees of glioma-specific splicing and included APPA4, CLTB, DYNC1I2, NF1, RTN4 and TNC." (PMID 18474104, 2008). "On univariate analysis, NF1 high-grade glioma patients who did not receive RT had inferior outcomes, though not significant on RMST." (PMID 41640172, 2026). "In this manner, Nf1-mutant neurons initiate a paracrine stromal cascade in which midkine induces CD8+ T cells to produce Ccl4, which in turn stimulates TAM expression of Ccl5, a cytokine that increases glioma growth." (PMID 41497446, 2025). "NF1 second hits were independent of those found in the clonal lesions (glioma, spindle cell lesion and café au lait spot)." (PMID 40000831, 2025). "This is particularly important for low-grade gliomas, like NF1-OPG, where reduced survival is not a factor, time-honored treatments typically result in excellent tumor control, and preservation of neurologic and functional outcomes is key." (PMID 41497446, 2025). "In pediatrics, unlike adults, genetic factors such as the presence of NF1 are a primary contributor to the formation of gliomas, and NF1 nearly always shows the presence of non-neoplastic FASIs." (PMID 39432071, 2024). "According to a previous report, observation is suggested for patients with neurofibromatosis type 1 (NF-1) or nonprogressive gliomas." (PMID 35223473, 2022). "Consistent with the negative correlation of FOSL1 and NF1 mRNA levels in IDH-wt gliomas, NF1-GRD overexpression in two independent MES GBM lines (BTSC 233 and BTSC 232) was associated with a significative downregulation of FOSL1 and FOSL1-regulated genes." (PMID 34399888, 2021). "In contrast, the RAS-MAPK signaling cascade seems to be a very promising target in NF1, at least in benign nerve sheath tumors, low grade gliomas and non-tumor lesions since RAS-MAPK activation is the main pathomechanism." (PMID 33863389, 2021). "Targeting RAS-downstream pathway signaling may provide opportunities for synergy across NF1 manifestations, as shown preclinically with MEK inhibition in plexiform neurofibromas, gliomas, and bone pathology." (PMID 31906320, 2020). "Interestingly, a study on gliomas arising in neurofibromatosis 1 (NF1) found the same frequent CDKN2A and ATRX genetic alterations in NF1 high-grade gliomas." (PMID 31677015, 2020). "We focused on these cells, since they are capable of generating glioma-like lesions in mice following transplantation, and no suitable primary human NF1-LGG cell lines are currently available for analysis." (PMID 32358581, 2020). "In the case of non‐glioma cell lines, NF1 community scores rarely deviate from the mean and do not vary by NF1 mutation status (Wilcoxon rank‐sum P > 0.05)." (PMID 30573688, 2018).
glioma (continued). "To begin to understand this role for NF1 loss in GBM, we performed an in vitro study of glioma cell lines and compared the results to non-transformed immortalized normal human astrocytes." (PMID 29643433, 2018). "Lastly, CCL5 is produced by microglia in the microenvironment of murine Nf1 optic glioma, and is increased in low-grade gliomas (pilocytic astrocytoma) relative to non-neoplastic tissue." (PMID 28380429, 2017). "Taken together, these results indicate that the increased NF1 and PTEN expression in IDH-mutant gliomas may be partly responsible for the improved patient survival compared with IDH-wildtype gliomas." (PMID 27852048, 2017). "When analyzed within IDH-mutant gliomas, however, NF1 and PTEN expression did not confer a survival advantage, suggesting that their correlation with improved survival is associated with IDH mutation-mediated increase in gene expression." (PMID 27852048, 2017). "We screen NF1 patients without non-optic gliomas every 2 years, patients with asymptomatic gliomas every 12 months, and patients with symptomatic gliomas every 6 months." (PMID 28202035, 2017). "These tumors are mainly grade I glial neoplasms, termed pilocytic astrocytomas, which are histologically similar to gliomas that arise sporadically in individuals without NF1." (PMID 27493794, 2016). "Similar to other LGG systems, the tumor microenvironment of Nf1 optic glioma consists of neoplastic cells (glioma cells and CSCs) and non-neoplastic stromal cells (neurons, endothelial cells, and monocytes)." (PMID 28066715, 2016). "This study shows that non-neoplastic Nf1+/− cells provide a permissive environment required for glioma formation." (PMID 25008045, 2014). "We detected the expression of NF1 in HeLa, HEB and the four glioma cell lines (U87MG, T98G, A172 and U251) and found that, with the exception of A172 cells, the NF1 mRNA and protein levels in glioma cells were low compared with HEB cells." (PMID 23185366, 2012). "Studies of low-grade gliomas (LGGs) using neurofibromatosis type 1 (NF1) as a genetic model system describe MDK as an upstream mediator regulating the activation of T cells, the release of cytokines, and thereby tumor growth in NF1-mutant murine and human neurons." (PMID 38098484, 2023). "Notably, ATRX protein expression was higher in the sporadic glioma lines (U251, SF188), while completely absent in the NF1-associated glioblastoma line JHH-NF1-GBM1." (PMID 35740680, 2022). "Therefore, further restricting the FGFR1 sequencing analysis to non-diffusely growing gliomas/MNGT tumors would yield 15% FGFR1 N546/K656 mutant cases after exclusion of cases with BRAF fusion, IDH1/2, NF1 or TERT mutation." (PMID 35018490, 2022). "Besides, mutation of phosphatase and tensin homolog deleted on chromosome ten (PTEN), neurofibromatosis (NF1), isocitrate dehydrogenase (IDH), B-Raf Proto-Oncogene (BRAF), and chromosome 1p19q co-deleted are common in glioma, even being used for molecular classification and prognosis prediction." (PMID 35785151, 2022). "Therefore, the lack of OPG formation likely reflects the failure of Nf1+/1809 neurons to produce glioma-promoting trophic factors." (PMID 35589737, 2022).